CYP2D6 (cytochrome P450 family 2 subfamily D member 6 (gene/pseudogene))
Diseases named in the same sentence as CYP2D6 in open-access papers (continued):
Sharing a sentence is not in itself a finding about the gene and the disease.
hepatocellular carcinoma (7 papers, 2015 to 2025). A malignant tumor that arises from hepatocytes. "From these, the variant rs3892097 in the liver enzyme CYP2D6 was selected because it is located within a genomic region that frequently undergoes LOH in several tumor types including hepatocellular cancers." (PMID 39368455, 2024). "Although an association between the cytochrome P4502D6 (CYP2D6) *10 (100C>T) polymorphism and hepatocellular carcinoma (HCC) is known, the mechanism remains unclear." (PMID 34412629, 2021). "Of these, talazoparib and MK-8776 demonstrated consistently heightened cytotoxic effects against cells with compromised CYP2D6 activity in engineered hepatocellular cancer cell models." (PMID 39368455, 2024). "Additional investigations utilizing in vitro models of hepatocellular carcinoma confirmed that talazoparib and MK-8776 consistently displayed cytotoxic effects against cells with compromised CYP2D6 activity." (PMID 39368455, 2024). "Moreover, talazoparib displayed CYP2D6 genotype dependent effects on primary hepatocellular carcinoma organoids." (PMID 39368455, 2024). "In order to explore the efficacy and safety of peony, effects of paeoniflorin and albiflorin (the principal components of peony) on cytochrome P450 (CYP) 3A4 and CYP2D6 were analyzed in human hepatoma HepG2 cells and evaluated from the level of recombinant CYP enzymes in vitro." (PMID 26089940, 2015). "HepaRG cells, a human hepatocellular carcinoma cell line, is the only cell line that can differentiate into hepatocyte‐like cells with high expression of CYP3A4 but poor expression of CYP2D6." (PMID 35174659, 2022). "Considering that talazoparib is already used in the clinical setting, and consistently demonstrated CYP2D6-dependent cytotoxicity in both HEK293T and HepG2 spheroids, we proceeded to culture and treat human hepatocellular cancer organoids from 11 patients with talazoparib (two-tailed t-test)." (PMID 39368455, 2024). "Among these, CYP2D6 stands out as a particularly promising target due to its frequent LOH in multiple tumor types, including hepatocellular carcinoma (HCC)." (PMID 39383606, 2024).
bipolar disorder (6 papers, 2016 to 2026). A disorder of the brain that causes unusual shifts in mood, energy, activity levels and the ability to carry out day-to-day tasks. "We propose to utilize pharmacogenetic testing as an intervention to aid in the identification of patients who are at risk of developing affective switching in bipolar disorder treated with selective serotonin reuptake inhibitors, CYP2D6 substrates, and inhibitors." (PMID 26871771, 2016). "Additionally, CYP2D6 is involved in the metabolism of neuroactive steroids implicated in both SCZ and bipolar disorder." (PMID 40126262, 2025). "Examples of clinically relevant CYP inhibitors in the management of bipolar disorder include valproate (CYP2C9), risperidone (CYP2D6), and SSRI such as fluoxetine (CYP2D6)." (PMID 38633030, 2024).
Cirrhosis (6 papers, 2016 to 2024). A chronic disorder of the liver in which liver tissue becomes scarred and is partially replaced by regenerative nodules and fibrotic tissue resulting in loss of liver function. "The presence of cirrhosis significantly affected CYP2D6 activity by causing a decrease in the Km value (21.4 vs. 28.9μM, respectively; P < 0.05) and an increase in the CLint value (8.4 vs. 3.5 μl/min/mg, respectively; P < 0.01) relative to controls." (PMID 27203676, 2016). "The allelic frequency of the CYP2D6*10 mutation was significantly reduced in HCC patients with fibrosis or cirrhosis relative to controls." (PMID 27203676, 2016). "The same changes were observed in HCC patients with fibrosis or cirrhosis, except CYP2D6, which had increased levels in patients with cirrhosis." (PMID 39062040, 2024). "The presence of fibrosis or cirrhosis significantly affected the CYP2D6 CLint value only, which was increased by 53.6% in patients with cirrhosis relative to those with fibrosis (8.4 vs. 3.9 μM, respectively; P < 0.05)." (PMID 27203676, 2016). "For patients with HCC accompanied by fibrosis or cirrhosis, the same activity changes were seen for the CYP isoforms, except for CYP2D6 which had higher values in HCC patients with cirrhosis." (PMID 27203676, 2016). "The results found that only the CL’H for CYP2D6 was significantly different between the fibrosis and cirrhosis groups, and was increased by 88.3% in patients with cirrhosis." (PMID 27086920, 2016). "Taken together, these results indicate that the effect of disease progression on CYP enzyme activities were not significantly different in HCC patients with fibrosis and cirrhosis, with the exception of CYP2D6." (PMID 27203676, 2016). "The Km of CYP2C8 was higher (25.7 vs. 21.4 μM; P < 0.05), but the value of CYP2D6 was lower (21.4 vs. 41.9 μM; P < 0.01) in the cirrhosis group relative to the fibrosis group, respectively." (PMID 27203676, 2016). "However, considering antiarrhythmic drugs such as flecainide, of which the main metabolic pathway involves CYP2D6, hepatic metabolism begins to decline notably in severe cirrhosis (Child-Pugh classification class C)." (PMID 39219880, 2024). "Moreover, CYP2D6 poor metabolizer genotypes were reported significantly more frequent in healthy subjects and carriers than in hepatitis/cirrhosis and HCC patients." (PMID 34412629, 2021). "In terms of Vmax, CYP2A6, CYP2B6, CYP2C9, CYP2D6, CYP2E1, and CYP3A4/5 were increased, while the Vmax values of CYP1A2 and CYP2C8 were decreased in both the cirrhosis and fibrosis groups compared to control subjects." (PMID 27203676, 2016). "Several previous studies reported that the activities of several CYPs, including CYP1A2, CYP2A6, CYP2D6, CYP2C19, CYP2E1, and CYP3A were decreased in cirrhosis patients relative to healthy subjects." (PMID 27203676, 2016). "Diseases that often accompany HCC, such as fibrosis and cirrhosis, did not affect CYP activity changes, except for CYP2D6 which had higher CLint values in the presence of cirrhosis." (PMID 27203676, 2016). "However, in the current study we found that the CYP2D6 CLint value from the cirrhosis patient subgroup was significantly higher than that for HCC patients without cirrhosis." (PMID 27203676, 2016). "Interestingly, the change in CYP2D6 activity between the cirrhosis and fibrosis groups was not consistent." (PMID 27203676, 2016). "CYP2D6 was not reported to be affected in non-cancerous liver diseases, except for protein levels in HCV cirrhosis." (PMID 34117631, 2021).
dementia (6 papers, 2012 to 2024). Loss of intellectual abilities interfering with an individual's social and occupational functions. "CYP2D6 metabolizes many psychiatric drugs, including antipsychotics and anti‐dementia drugs." (PMID 38978357, 2024). "CYP2D6, CYP2C9, CYP2C19, and CYP3A4/5 geno-phenotypes are involved in the metabolism of over 90% of drugs currently used in patients with dementia, and only 20% of the population is an extensive metabolizer for this tetragenic cluster." (PMID 32357528, 2020).
epilepsy (6 papers, 2022 to 2025). A brain disorder characterized by episodes of abnormally increased neuronal discharge resulting in transient episodes of sensory or motor neurological dysfunction, or psychic dysfunction. "The study identified three anti-glucose drug target genes, ETFDH, CYP21A2 and CYP2D6, associated with epilepsy." (PMID 38167102, 2024). "It was discovered that three antidiabetic drug target genes, ETFDH, CYP21A2 and CYP2D6, were involved in the occurrence of epilepsy." (PMID 38167102, 2024). "Conversely, the CYP2D6 gene was found to be a protective factor for epilepsy in both the discovery set (IVW, OR = 0.0984, 95% CI, 0.969–0.998, p = 0.025) and replication set (IVW, OR = 0.977, 95% CI, 0.955–1.000, p = 0.046)." (PMID 38167102, 2024). "An experimental study showed an overexpression of CYP3A4, CYP2C9, and CYP2E1 in human brain microvascular endothelial cells of drug‐resistant patients with epilepsy while CYP2D6 and CYP2C19 were downregulated." (PMID 34560816, 2022). "Meanwhile, CYP2D6 may act as a protective factor for epilepsy." (PMID 38167102, 2024). "Specifically, patients of epilepsy with different genotypes of CYP2D6*10 not reaching the minimum effective plasma concentration and those exceeding the minimum toxic concentration are compared to investigate their genetic polymorphisms." (PMID 35290166, 2022).
Hypertension (6 papers, 2016 to 2024). The presence of chronic increased pressure in the systemic arterial system. "Considering the CYP2D6 gene, the absence of the C allele (T/T genotype) was associated with increased weight and the occurrence of hypertension." (PMID 26880915, 2016). "The commonly prescribed drugs for hypertension (Propranolol, Metoprolol, Telmisartan, Losartan) and T2DM (Glimepiride, and Pioglitazone) shares the same drug metabolizing enzymes (CYP1A2, CYP3A4, CYP2C9, and CYP2D6)." (PMID 34115763, 2021).
liver cancer (6 papers, 2020 to 2024). An epithelial or non-epithelial malignant neoplasm that arises from the liver. "Neither CYP2D6 nor HNF4A had SNPs related to the health disparity between the two ethnic groups obviating the implication of CYP2D6 polymorphism in the inequalities of liver cancer in AS and CA." (PMID 34597305, 2021). "It is also imperative to dissect the inherent causes of liver cancer in AS and CA, and their effect on CYP2D6 activity and inflammatory responses." (PMID 34597305, 2021). "With respect to the liver, few reports have claimed a significant association between CYP2D6 polymorphism and the development of liver cancer." (PMID 34597305, 2021). "Elevated IL6 expression in CA patients may imply an initial hepatic inflammation due to HBV/HCV that may have progressed to liver cancer; while the increased levels of CYP2D6 in AS may be due to another underlying problem like alcohol or metabolic syndrome." (PMID 34597305, 2021). "Therefore, it is of paramount importance to delineate the predominant cause of liver cancer in distinct populations, and to investigate how the underlying cause can affect the expression and activity of CYP2D6, and the release of proinflammatory cytokines, mainly IL6." (PMID 34597305, 2021). "Based on these facts, targeting CYP2D6 has emerged as a potential therapeutical approach for liver cancer." (PMID 37601910, 2023). "CYP2D6 is known to metabolize several drugs used in the treatment of liver cancer, such as tamoxifen, codeine, and oxycodone." (PMID 37601910, 2023). "Once elucidated, we will have a better understanding of the way CYP2D6 modulates liver cancer and inflammation; thus, leading to better assessment of drugs interactions and conduct of efficient therapies with minimal side effects." (PMID 34597305, 2021). "Given CYP2D6 significant role in drug clearance, evaluation of CYP2D6 in liver cancer patients of diverse backgrounds must be prioritized to ensure the proper application of pharmacotherapeutics in precision medicine." (PMID 34597305, 2021). "Our results positions CYP2D6 at the intersection between inflammation and liver cancer in AS and CA patients." (PMID 34597305, 2021). "Its negative association with IL6 proclaims an intricate relationship between CYP2D6 and inflammation in the ethnic differences seen in AS and CA liver cancer patients." (PMID 34597305, 2021). "To decipher the role of CYP2D6 in the disparity of liver cancer incidence and outcome between AS and CA, we imported the DESeq2 differentially expressed dataset of 559 genes into the Ingenuity Pathway Analysis (IPA) tool." (PMID 34597305, 2021). "Multiple lines of evidence suggest that CYP2D6 may be involved in various mechanisms that could potentially contribute to the progression of liver cancer." (PMID 37601910, 2023). "Being the highest significantly DEG among the two populations, CYP2D6 may serve as a putative biomarker for liver cancer disparities." (PMID 34597305, 2021). "Therefore, it is the gene expression level of CYP2D6 that contributes to the liver cancer health disparity." (PMID 34597305, 2021). "It has been demonstrated that the frequency of CYP2D6-inactivating mutations is significantly lower among liver cancer patients than in healthy controls and cirrhotic subjects who did not develop liver cancer." (PMID 34412629, 2021). "Moreover, combining talazoparib with currently utilized drugs for liver cancer may potentially enhance treatment outcomes for patients who have lost CYP2D6 activity in their tumor." (PMID 39368455, 2024). "Herein, we report that CYP2D6 may serve as a putative biomarker in liver cancer health disparities." (PMID 34597305, 2021). "Therefore, CYP2D6 may serve as a putative biomarker in liver cancer health disparities." (PMID 34597305, 2021). "Our findings suggest an intricate interplay between the genes CYP2D6, HNF4A, and IL6 in AS and CA liver cancer patients." (PMID 34597305, 2021).
liver cancer (continued). "Although these preliminary results require further validation, CYP2D6 and IL6 might have significant clinical impact in the management of liver cancer incidence and application of personalized treatment regimens." (PMID 34597305, 2021). "The high levels of CYP2D6 in AS and IL6 in CA suggest variability in liver cancer etiology." (PMID 34597305, 2021). "However, assessment of CYP2D6 in liver cancer patients with different racial/ethnic backgrounds has not been reported." (PMID 34597305, 2021). "Although the expression of HNF4A was not significantly different between AS and CA liver cancer patients in our study, our IPA analysis did identify HNF4A as an upstream regulator of CYP2D6." (PMID 34597305, 2021).
liver disease (6 papers, 2016 to 2025). "For example, genetic testing for CYP2D6 variations can help guide beta-blocker treatments for portal hypertension." (PMID 40430206, 2025). "The pharmacokinetic study, which revealed unaltered pharmacokinetics of debrisoquine (substrate of CYP2D6) in mild or moderate (Child–Pugh classification) liver disease patients also corroborate our results." (PMID 36901973, 2023). "This study demonstrated that CYP1A2, CYP2C19, CYP2D6, and CYP2E1 enzyme activity was differentially affected by the presence of liver disease." (PMID 36901973, 2023). "Activities of CYP2E1, CYP2D6, CYP1A2 and CYP2C19 were all found to decrease with increasing hepatic disease severity, their activities were differentially affected." (PMID 27754327, 2016). "Consequently, these combined findings indicate that starting doses of CYP2D6, CYP2E1 and CYP3A4 substrates should be adjusted in patients with moderate or severe liver disease, whereas a dose reduction of CYP2C19 and CYP1A2 substrates should already be considered in milder forms of liver disease." (PMID 27754327, 2016).
mental disorder (6 papers, 2012 to 2025). A disease that has its basis in the disruption of mental process. "In conclusion, this study represents the first large-scale evaluation of clinically actionable CYP2D6 and CYP2C19 variants in a Central Indian population with common mental disorders." (PMID 41378208, 2025). "This study presents the first comprehensive analysis of the prevalence and clinical relevance of clinically actionable CYP2D6 and CYP2C19 alleles, genotypes, and predicted metabolizer phenotypes in a Central Indian population of 509 individuals diagnosed with common mental disorders." (PMID 41378208, 2025). "Despite the discordance, both the wider literature and our study showed that approximately 73%–85% of patients with mental disorders carry non-NM phenotypes in CYP2D6 and/or CYP2C19." (PMID 36895946, 2023).
Alzheimer disease (5 papers, 2012 to 2024). A progressive, neurodegenerative disease characterized by loss of function and death of nerve cells in several areas of the brain leading to loss of cognitive function such as memory and language. "The variant rs601338 in FUT2 has been associated with resistance to Norwalk virus infection, rs10774671 in OAS1 with diabetes type 1 susceptibility, rs3892097 in CYP2D6 with poor metabolism of debrisoquine, and rs3832852 in A2M with the pathogenesis of Alzheimer's disease." (PMID 39368455, 2024). "This study detected the involvementof genes associated with Alzheimer’s disease (MEF2Cand EXOC4 genes) and schizophrenia (MEF2C, CYP2D6,FAM109B, SEPT3, NAGA, TCF20, and NDUFA6 genes)." (PMID 33659785, 2020). "Thus the inducible CYP2D6 model was used to perform a B cell epitope mapping at several defined times after initiation of the disease (i.e., Ad-2D6 infection) in order to reveal to which CYP2D6 epitope antibodies are generated first." (PMID 27916939, 2016).
autism spectrum disorder (5 papers, 2021 to 2024). A spectrum of developmental disorders that includes autism, and Asperger syndrome. "Similar results have been reported for children with autism spectrum disorders treated with risperidone, in that those with the CYP2D6*5/*10, CYP2D6*10/*10, or CYP2D6*10/*41 alleles exhibited higher levels of risperidone after administration." (PMID 33535976, 2021). "A study based on 97 Thai children and adolescents with autism spectrum disorder suggested that CYP2D6 genotypes were independent of the risperidone plasma concentrations or the total active moiety levels." (PMID 34867511, 2021).
heart failure (5 papers, 2010 to 2025). Inability of the heart to pump blood at an adequate rate to meet tissue metabolic requirements. "For instance, in patients with CYP2D6 poor metabolizer enzyme, beta-blockers such as metoprolol and propranolol can cause a rash, bradyarrhythmia, shortness of breath, hypotension and heart failure." (PMID 32708157, 2020). "A patient receiving concomitant metoprolol and propafenone (CYP2D6 inhibitor) was diagnosed as having global heart failure with atrial fibrillation with slow ventricular response." (PMID 40287796, 2025).
non-small cell lung carcinoma (5 papers, 1999 to 2025). A group of at least three distinct histological types of lung cancer, including non-small cell squamous cell carcinoma, adenocarcinoma, and large cell carcinoma. "In one cohort, non-small cell lung cancer patients carrying low-function CYP2D6 genotypes had a significantly increased risk of ≥Grade 2 rash during gefitinib therapy compared to those with normal CYP2D6 activity." (PMID 41295218, 2025). "Depletion of CYP2D6 influences the genes involved in EMT, oncogenesis and immune-related pathways and acts as a biomarker for drug resistance in non-small cell lung cancer." (PMID 35874705, 2022). "Gefitinib, an anticancer agent clinically prescribed to treat non-small-cell lung cancer, is a substrate of P-glycoprotein (P-gp) and breast cancer resistance protein (BCRP), and metabolized mainly by cytochrome P450 (CYP) 3A4 and CYP2D6." (PMID 36144507, 2022).
anxiety disorder (4 papers, 2016 to 2025). A category of psychiatric disorders which are characterized by anxious feelings or fear often accompanied by physical symptoms associated with anxiety. "Our findings indicate a significant role of the CYP2D6 gene polymorphisms in predicting the reduction in anxiety disorders, interestingly without a clear influence on the reduction in depressive symptoms during duloxetine therapy among patients with MDD." (PMID 37686266, 2023). "Current evidence from large genome-wide association studies (GWAS) does not support a causal or enrichment association between CYP2D6 or CYP2C19 variants and psychiatric disorders such as major depressive disorder (MDD) or anxiety disorders." (PMID 41378208, 2025).